MIR6737 (microRNA 6737)
Synonyms: hsa-mir-6737
Gene: MicroRNA gene on chromosome 1 (153,962,351 to 153,962,420, reverse strand). Ensembl gene ENSG00000276584.
Homologues: Orthologues: chimpanzee MIR6737 (100% identical).